HLA-K (major histocompatibility complex, class I, K (pseudogene))
Synonyms: HLA-70; HLA70; HLAK
Gene: Transcribed unprocessed pseudogene on chromosome 6 (29,926,459 to 29,929,232, forward strand). Ensembl gene ENSG00000230795.
Diseases named in the same sentence as HLA-K in open-access papers:
HLA-K is named in the same sentence as 4 diseases in open-access papers, as found by Europe PMC text mining. Sharing a sentence is not in itself a finding about the gene and the disease. The quoted sentences say what the papers report.
breast carcinoma (2 papers, 2020 to 2021). "Individually, HLA-K has the most prognostic utility in breast cancer since median separation splits the patients (50.1 to 49.9%)." (PMID 32241256, 2020). "Considering HLA genes are directly related to patient response to immunotherapy in lung cancer and disease free survival in breast cancer, HLA-K should be further investigated." (PMID 32241256, 2020). "We find that increased CTSLP8 (Wald p-value = 5.0 × 10− 05), increased EEF1GP4 (Wald p-value = 1.0 × 10− 06), decreased HLA-K (Wald p-value = 8.0 × 10− 05), increased CBX1P3 (Wald p-value = 1.0 × 10− 03), and increased RPS10P20 (Wald p-value = 2.0 × 10− 03) indicate worse prognosis in breast cancer." (PMID 32241256, 2020).
melanoma (1 paper, 2023). A malignant, usually aggressive tumor composed of atypical, neoplastic melanocytes. "Some of these include Dead H box helicase 11 (DDX11), Claudin 5 (CLDN5), chemokine CXC motif (CXCL1 ligand 1, melanoma growth), glutathione S-transferase mu 1 (GSTM1), major histocompatibility complex class I K (HLA-K), and thrombospondin 1 (THBS1)." (PMID 36769056, 2023).
HLA-K also shares sentences with these, for which no sentence is quoted: lung carcinoma (1 paper); schizophrenia (1).